BDNF (brain derived neurotrophic factor)
Diseases named in the same sentence as BDNF in open-access papers (continued):
Sharing a sentence is not in itself a finding about the gene and the disease.
schizophrenia (continued). "Quantitative real-time PCR analysis of RNA in 100 individuals (35 with schizophrenia, 31 with bipolar disorder, and 34 psychiatrically normal controls) showed significantly decreased expression of Sprouty2 and BDNF in both schizophrenia and bipolar disorder." (PMID 18335055, 2008). "Postmortem studies showed changes in BDNF as well as its receptor, TrkB expression in different brain areas of subjects with schizophrenia." (PMID 18335055, 2008). "In another study, both BDNF and TrkB mRNA levels were significantly decreased in the prefrontal cortex of subjects with schizophrenia." (PMID 19506725, 2008). "BDNF plays an important role in regulating dopaminergic, glutamatergic, and other neuronal signaling pathways, alterations of which are observed in schizophrenia." (PMID 18335055, 2008). "Second, a significant positive correlation was observed between Spry2 and BDNF in schizophrenia, bipolar and normal subjects." (PMID 18335055, 2008). "Significant high correlation between Spry2 and BDNF mRNA expression levels was found in schizophrenia group (p = 0.01), bipolar group (p = 0.02) and control group (p = 0.016)." (PMID 18335055, 2008). "The changes in Spry2 mRNA expression were significantly correlated with BDNF mRNA expression in schizophrenia, bipolar and normal subjects suggesting the importance of BDNF in the regulation of Spry2 expression." (PMID 18335055, 2008). "Although these results did not directly test genetic mechanisms, other studies have highlighted how genes implicated in schizophrenia (e.g., AKT1, BDNF) may render the fetus more vulnerable to hypoxic insult." (PMID 41073801, 2026). "However, the role of gut microbiota, SCFAs, and BDNF in chronic ketamine-induced schizophrenia-like behaviors is unclear." (PMID 42022121, 2026). "BDNF is currently one of the most extensively studied biomarkers for schizophrenia." (PMID 40375951, 2025). "Our study revealed that serum BDNF levels were negatively correlated exclusively with the language domain and not with other cognitive domains, suggesting a specific role of BDNF in language function in patients with schizophrenia." (PMID 40082848, 2025). "We hypothesised that these reductions in BDNF and TrkBTK+ mRNA also exist in the ventral midbrain in schizophrenia, a region of concentrated dopamine neurons." (PMID 40335479, 2025). "It is tempting to postulate that an enhanced apoptosis, involving the pro-BDNF-FasL link and the p75NTR receptor, may characterize pharmaco-resistant schizophrenia." (PMID 41010622, 2025). "Disturbed BDNF signaling is implicated in schizophrenia pathogenesis; however, the available data are not fully coherent." (PMID 41010622, 2025). "BDNF is aberrantly regulated in the central nervous system of animal models of schizophrenia, and it has been observed that fewer BDNF-positive neurons are present in schizophrenia patients." (PMID 41170387, 2025). "The neurotrophic hypothesis of schizophrenia posits that the alterations observed in the brains of individuals with schizophrenia stem from disruptions in developmental processes involving BDNF." (PMID 40867109, 2025). "Dysregulated transcription of BDNF in schizophrenia may be directly related to NURR1 as NURR1 is a transcription factor for the BDNF gene and NURR1 mRNA is also decreased in the midbrain in schizophrenia cases with high inflammation." (PMID 40335479, 2025). "However, co-treatment with nicotine occludes olanzapine’s BDNF-enhancing effect, highlighting complexities relevant to smoking comorbidity in schizophrenia." (PMID 40806385, 2025). "Indeed, BDNF and TrkB reductions are correlated with deficits in inhibitory neuron transcripts in the cortex of people with schizophrenia." (PMID 40335479, 2025). "Reduced expression of BDNF has been identified in the frontal cortex and hippocampus in patients with schizophrenia, and studies have found that BDNF may play a role in the neuropsychological functions of schizophrenic." (PMID 40392301, 2025).
schizophrenia (continued). "Such discrepancies may in part reflect methodological and clinical sources of heterogeneity, as previously reported in research on peripheral BDNF levels in schizophrenia." (PMID 41008288, 2025). "Nevertheless, BDNF may play a significant role in this disorder, as alterations of BDNF levels have been observed in patients diagnosed with schizophrenia." (PMID 41254423, 2025). "Comparison of BDNF gene expression within clusters across immune subgroups of schizophrenia cases and controls revealed that BDNF mRNA was primarily localised to neuronal clusters across all three subgroups, with occasional expression of BDNF evident in some astrocyte subtypes." (PMID 40335479, 2025). "Thus, it has been shown that patients with schizophrenia have decreased concentrations of BDNF in HPC and PFC." (PMID 40867109, 2025). "In conclusion, non-convulsive electroconvulsive therapy combined with drug therapy has a significant effect in the therapy of schizophrenia, which can effectively improve psychiatric symptoms and cognitive function of patients, regulate serum BDNF and S100B levels, and is safe." (PMID 41312344, 2025). "Similarly, only one study has concurrently measured brain-derived neurotrophic factor (BDNF) alongside vitamin D in patients with schizophrenia." (PMID 40867540, 2025). "We postulate that in the early stages of schizophrenia, NGF and BDNF are primarily linked to neurodevelopment, while in the chronic phase, their levels may be modulated by antipsychotic medication." (PMID 40082848, 2025). "However, further investigation into the specific subtypes of neurons where reductions in BDNF mRNA are localised in the schizophrenia midbrain is warranted." (PMID 40335479, 2025). "Overall, schizophrenia may represent a more homogeneous diagnostic entity than UHR, which could account for the consistent BDNF level findings in schizophrenia but the more variable results in UHR." (PMID 41008288, 2025). "Additionally, polyphenols can activate the BDNF/TrkB pathway; for instance, curcumin upregulates BDNF expression in the hippocampus via the Wnt/β-catenin signaling pathway, reversing schizophrenia-like phenotypes." (PMID 40612741, 2025). "Notably, it reverses the reduction of BDNF levels induced by ketamine in schizophrenia models, highlighting its therapeutic potential." (PMID 40612741, 2025). "The observed reduction in NGF-β and BDNF levels may indicate diminished neurotrophic support in schizophrenia patients." (PMID 40082848, 2025). "Blockade of 5-HT2ARs, a defining pharmacological feature of atypical antipsychotics, has been linked to elevated hippocampal BDNF levels correlating with improvements in the cognitive and negative symptoms of schizophrenia." (PMID 40806385, 2025). "Moreover, the expression levels of BDNF found in the peripheral blood of patients with schizophrenia are related to the extent of cognitive impairment." (PMID 40612741, 2025). "It was recently shown that the BDNF gene rs6265 (C → T, Val → Met) polymorphism can be associated with the severity of affective and non-affective symptoms of schizophrenia." (PMID 41010622, 2025). "MiR-30a-5p and miR-195 may regulate the gene expression of brain-derived neurotrophic factors (BDNF), so it is suggested that miR-195 may be involved in the pathogenesis of schizophrenia by regulating BDNF46." (PMID 40379790, 2025). "Studies on DNA methylation and histone modification of the BDNF gene indicate that individuals with schizophrenia may synthesize reduced levels of BDNF." (PMID 41455872, 2025). "Variations in BDNF may lead to changes in the brains of patients with schizophrenia, including a reduction in the volume of frontal grey matter and an increase in the volume of lateral ventricles and sulcal cerebrospinal fluid (CSF)." (PMID 40867109, 2025). "Both decreased and unaltered BDNF levels were reported in schizophrenia." (PMID 41010622, 2025).
schizophrenia (continued). "BDNF, a neurotrophin critical for neuronal survival, migration, differentiation, and synaptic plasticity, is regulated by DISC1, a schizophrenia risk gene modulated by HERV-W env through calcium-dependent Transient receptor potential canonical 3(TRPC3) channel activation." (PMID 41200560, 2025). "This study investigates factors influencing suicidal ideation in first‐episode schizophrenia patients, focusing on cognitive function, brain‐derived neurotrophic factor (BDNF), triglyceride (TG), and total cholesterol (TC) in patients with first‐episode schizophrenia." (PMID 38680078, 2024). "The fact that BDNF levels declined in long-term schizophrenia individuals affirms the idea that BDNF may have a role in the pathogenesis of the disease." (PMID 37287291, 2024). "Additionally, BDNF has been implicated in the pathophysiology of SCZ, with increased serum levels observed in chronic institutionalized patients with schizophrenia." (PMID 38592583, 2024). "Consequently, BDNF has been extensively studied in both a therapeutic target and a biomarker for schizophrenia." (PMID 39125882, 2024). "Finally, at the end of this article, we summarised the role of BDNF as a protective agent against various neurological disorders, including schizophrenia, AD, PD, and HD." (PMID 37287291, 2024). "The 5mC of the BDNF gene could be regulated by environmental conditions and was believed to be involved in the pathogenesis of schizophrenia." (PMID 38203806, 2024). "Further research examining the connection between BDNF and brain volume changes in schizophrenia could enhance our understanding of the disorder’s pathophysiology and potentially inform the development of new therapeutic strategies." (PMID 39935805, 2024). "Plasma brain‐derived neurotrophic factor (BDNF) level may be a potential biomarker of cognitive recovery in acute schizophrenia." (PMID 38680078, 2024). "However, using serum or plasma levels of BDNF as a biomarker presents challenges due to the release of BDNF from human blood platelets, leading to varied results in studies analyzing BDNF levels in schizophrenia patients." (PMID 39125882, 2024). "Transplantation of serum exosomes from patients with schizophrenia into normal mice can lead to changes in BDNF gene expression in the hippocampus and prefrontal cortex of mice, and hsa-miR-206 in exosomes can regulate BDNF expression." (PMID 38707431, 2024). "Furthermore, BDNF is secreted from these neurons to the striatum, where it regulates the expression of the dopamine receptor D3, which is overexpressed in schizophrenia patients." (PMID 39125882, 2024). "Deficiency of this neurotrophic factor could lead to morphological and chemical disturbances in the brain, which would be the basis of the mental illness of neuropathology in schizophrenia, as supported by the reduced BDNF levels in schizophrenia patients." (PMID 37287291, 2024). "A Schizophrenia-associated genetic variant in the 3′UTR of the human furin gene, a kpc-1 homologous gene, was recently shown to result in downregulation of furin expression by acquiring a miR-338-3p binding site, leading to reduced BDNF production." (PMID 39110773, 2024). "Similarly, there is abundant research describing the relationship of BDNF with other psychiatric disorders, mostly in terms of pathophysiology, but also as a biomarker predictor of response to treatment, notably Schizophrenia (SCZ) and Bipolar Disorder (BD)." (PMID 39456983, 2024). "Moreover, higher levels of BDNF are positively correlated with a better course of disease in patients with schizophrenia." (PMID 38376038, 2024). "Despite BDNF playing a critical role in the development and functionality of cortical parvalbumin neurons, the relationship between BDNF signaling impairments in these neurons and schizophrenia remains largely uncharacterized." (PMID 39125882, 2024).
schizophrenia (continued). "Additionally, research has found that patients with schizophrenia have significantly lower BDNF levels and higher IL-8 serum levels compared to individuals without schizophrenia." (PMID 38793070, 2024). "In conclusion, the cognitive benefits of exercise in schizophrenia could be due to exercise stimulating neurogenesis, perhaps by up-regulating BDNF." (PMID 39517406, 2024). "Several meta-analyses have previously found a higher risk for schizophrenia in Met/Met carriers of non-synonymous Val66Met polymorphism in BDNF, although others have not reported any association." (PMID 37109044, 2023). "Lower BDNF levels were reported to be correlated with executive control dysfunction, which was measured using verbal fluency tests and Wisconsin card sorting tests in patients with schizophrenia." (PMID 37114226, 2023). "Predicting relapse in schizophrenia: is BDNF a plausible biological marker?" (PMID 37077958, 2023). "As well-known, the BDNF-TrkB signaling pathway was attenuated in schizophrenia." (PMID 37168420, 2023). "In schizophrenia, reduced BDNF levels have been found in the prefrontal cortex and hippocampus." (PMID 36979300, 2023). "The analysis of the second BDNF genetic variant rs962369 did not confirm its association with schizophrenia in any of the five genetic models nor after sex stratification." (PMID 37626739, 2023). "Therefore, measuring plasma BDNF levels is a valid model for studying the role of neurotrophins in schizophrenia patients." (PMID 37445746, 2023). "However, the post-mortem brain tissue of individuals with schizophrenia showed dissimilar results, with some studies reporting BDNF increases in the prefrontal cortex and the hippocampus, while others noted BDNF decreases in these parts of the brain." (PMID 37763162, 2023). "Thus, the role of BDNF levels on cognition and pathogenesis in schizophrenia remains to be investigated further." (PMID 37234686, 2023). "BDNF had a nourishing effect on nerve cells, and its level and mRNA expression were both decreased in the peripheral blood of schizophrenic patients, which indicates possible neuratrophy in the pathogenesis of schizophrenia that induces brain injury." (PMID 37013544, 2023). "Previous studies have reported alterations in the expression of plasticity-associated genes such as BDNF, NGF, VEGF, and NRG1 in the blood of individuals with schizophrenia, which may provide new evidence for synaptic plasticity dysfunction in schizophrenia." (PMID 37990254, 2023). "Several studies, along with a meta-analysis, have previously identified a higher risk for schizophrenia in individuals carrying the Met/Met variant of the non-synonymous Val66Met SNP in the BDNF gene." (PMID 37626739, 2023). "Individuals with schizophrenia typically exhibit reduced blood levels of BDNF." (PMID 37892465, 2023). "Our meta-analysis showed that treatment with ECT therapy and antipsychotic medication increases serum BDNF levels in patients with drug-resistant schizophrenia compared to patients treated with medication only; however, this effect is not statistically significant." (PMID 37685795, 2023). "Moreover, the brain-derived neurotrophic factor (BDNF) was described as a potential blood-based biomarker regarding diagnosis as well as treatment of schizophrenia." (PMID 37298866, 2023). "Summary of BDNF and schizophrenia co-citation network (Clusters 1–3)." (PMID 37077958, 2023). "Despite the attributes of the schizophrenia, few studies have been undertaken to investigate whether there is a difference in serum BDNF level between early responders and early non‐responders to antipsychotic drug in first‐episode patients with schizophrenia." (PMID 37485797, 2023). "BDNF is known to involve in the pathological mechanism of cognitive function, and its peripheral levels can serve as a index for the assessment of cognition in schizophrenia." (PMID 37809845, 2023).
schizophrenia (continued). "Our study suggests that BRB can alleviate memory deficits induced by T. gondii infection or Ket, probably through the alterations in BDNF expression that might be involved in the behavioral changes leading to schizophrenia." (PMID 37649038, 2023). "What are the important strong research areas in the field of BDNF and schizophrenia?" (PMID 37077958, 2023). "Moreover, and interestingly, some show an increase of BDNF levels in the cingulate cortex or hippocampus of schizophrenia." (PMID 37485797, 2023). "The BDNF and schizophrenia publications show an overall upward trend that peaks in 2021." (PMID 37077958, 2023). "What are the main subjects and themes of the research on BDNF and schizophrenia?" (PMID 37077958, 2023). "Serum level of BDNF could be used to differentiate between schizophrenia and methamphetamine addiction when clinical distinctions are challenging to detect." (PMID 37520481, 2023). "However, they did discover a significant association between the combination of the BDNF gene (rs6265 AA/AG) and the TNF-α gene (rs1799964 CC/CT) and the development of schizophrenia." (PMID 37763162, 2023). "Based on these results, we may conclude that a low level of BDNF is likely to mediate in the neurodevelopmental pathway of schizophrenia by affecting new neuron development, synaptogenesis and neuronal communication." (PMID 37685795, 2023). "Previous existing data about serum BDNF levels in schizophrenia patients have been controversial." (PMID 37485797, 2023). "Experimental and clinical studies have suggested that BDNF may serve as a biomarker also in neuropsychiatric disorders such as schizophrenia." (PMID 37109038, 2023). "A general rising trend in the number of publications was found in BDNF and schizophrenia research." (PMID 37077958, 2023). "Another important inference in this cluster is related to biomarkers for schizophrenia that include peripheral (BDNF/neurotrophic factor, matrix metallopeptidase 9 (MMP-9), cytokine, oxidative stress) and neuroimaging (magnetic resonance imaging (MRI), cortical thickness) biomarkers." (PMID 37077958, 2023). "Indeed, the ameliorated expression of BDNF has been shown to occur in several neurodegenerative diseases, including cerebellar pathologies such as spinocerebellar ataxia type 6, schizophrenia, and bipolar disorder state." (PMID 35794426, 2023). "The authors believe that more studies should focus on other types of psychotic disorders than schizophrenia, especially on the first episode, as well as drug-naïve patients, as previous medication may influence BDNF levels." (PMID 36767478, 2023). "In a broader way, a deeper understanding of BDNF’s role in schizophrenia could inform the development of BDNF-based strategies for the prevention and treatment of this disorder." (PMID 37445746, 2023). "It is possible that measuring BDNF levels in the brain itself may provide a better understanding of the role of BDNF in schizophrenia." (PMID 37520481, 2023). "To examine whether the analyzed mental disorders differ in their genetic overlap, we performed a comparative analysis between MDD subtypes, and we also compared BDNF variants between MDD subtypes and schizophrenia." (PMID 37626739, 2023). "Notably, the frequency of minor allele C of BDNF rs962369 varied across subgroups, with the highest frequency in patients with recurrent MDD (0.32) and the lowest in schizophrenia patients (0.20)." (PMID 37626739, 2023). "Researchers from China and the United States have mostly researched BDNF and schizophrenia." (PMID 37077958, 2023). "Also, in drug-naive first-episode schizophrenia, BDNF concentration is decreased as administration with antipsychotic drugs normalizes its level." (PMID 37685795, 2023). "Additionally, BDNF has been investigated as a possible biomarker in cognition diagnosis and evaluation of schizophrenia." (PMID 37077958, 2023). "There is also evidence that BDNF has a possible role in the pathophysiology of schizophrenia." (PMID 35757201, 2022).